PHOX2A (paired like homeobox 2A)
Description:
May be involved in regulating the specificity of expression of the catecholamine biosynthetic genes. Involved in the development of several major noradrenergic neuron populations, including the locus coeruleus. Acts as a transcription activator/factor. Could maintain the noradrenergic phenotype (By similarity).
Synonyms: ARIX; PMX2A; CFEOM2; FEOM2
Tractability: No criterion of Open Targets' tractability assessment is met for any kind of drug.
Gene: Protein-coding gene on chromosome 11 (72,239,077 to 72,245,664, reverse strand). Ensembl gene ENSG00000165462.
Subcellular location: Nucleus
Subcellular location (Human Protein Atlas): Nucleoplasm
Gene Ontology:
Molecular function: DNA-binding transcription activator activity, RNA polymerase II-specific; protein binding; RNA polymerase II transcription regulatory region sequence-specific DNA binding; sequence-specific double-stranded DNA binding; DNA-binding transcription factor activity; DNA-binding transcription factor activity, RNA polymerase II-specific; DNA binding
Biological process: positive regulation of transcription by RNA polymerase II; regulation of transcription by RNA polymerase II; dopaminergic neuron differentiation; neuron development; noradrenergic neuron differentiation; oculomotor nerve formation; regulation of DNA-templated transcription; trochlear nerve formation
Cellular component: chromatin; nucleoplasm; nucleus
Genetic constraint (gnomAD): Loss-of-function variants: 13 observed, 10.28 expected, observed/expected ratio (o/e) 1.26, 90% interval 0.81 to 1.84. The synonymous counts are far from expectation, so gnomAD's model fits this gene poorly and the ratio says little. Missense variants: 361 observed, 264.83 expected, observed/expected ratio (o/e) 1.36, 90% interval 1.25 to 1.49. Synonymous variants: 219 observed, 144.82 expected, observed/expected ratio (o/e) 1.51, 90% interval 1.35 to 1.69.
Homologues: Orthologues: chimpanzee PHOX2A (100% identical), macaque PHOX2A (99% identical), dog PHOX2A (99% identical), pig PHOX2A (99% identical), rat Phox2a (97% identical), guinea pig PHOX2A (97% identical), mouse Phox2a (97% identical), rabbit PHOX2A (92% identical), zebrafish phox2a (65% identical), tropical clawed frog phox2a (52% identical), Caenorhabditis elegans ceh-17 (29% identical). Paralogues in human: PHOX2B (59% identical), ARX (29% identical), DRGX (29% identical), UNCX (27% identical), ALX4 (26% identical), RAX (26% identical), OTX1 (25% identical), PAX7 (25% identical), PRRX1 (25% identical), PRRX2 (24% identical), ALX3 (24% identical), PITX1 (24% identical), and 38 more.
Diseases named in the same sentence as PHOX2A in open-access papers:
PHOX2A is named in the same sentence as 30 diseases in open-access papers, as found by Europe PMC text mining. Sharing a sentence is not in itself a finding about the gene and the disease. The quoted sentences say what the papers report.
neuroblastoma (11 papers, 2016 to 2025). Neuroblastoma (NB) is the most common solid, extracranial childhood tumor. "The overexpression of PHOX2A has been demonstrated in neuroblastoma, both in tumour samples and in neuroblastoma cell lines." (PMID 41146049, 2025). "PHOX2B and its paralogue gene PHOX2A are two homeodomain proteins in the network regulating the development of autonomic ganglia that have been associated with the pathogenesis of neuroblastoma (NB), because of their over-expression in different NB cell lines and tumour samples." (PMID 26902400, 2016). "These NIPBL-bound MYCN peaks are highly enriched for motifs of core regulatory circuitry (CRC) transcription factors such as GATA3, PHOX2A, HAND1, and HAND2, which contribute to the maintenance of the neuroblastoma oncogenic cell identity." (PMID 40867243, 2025). "In contrast, NIPBL peaks that overlapped with MYCN binding were significantly enriched for motifs recognized by core regulatory circuitry (CRC) transcription factors critical to neuroblastoma cell identity, including GATA3, PHOX2A HAND1, and HAND2." (PMID 40867243, 2025). "GATA2 has been identified as a component of the transcriptional regulatory circuits involving super enhancers in neuroblastoma cells, which also includes GATA3, PHOX2A, PHOX2B, and HAND2." (PMID 36980710, 2023). "In neuroblastoma, our analysis identified the transcription factors ISL1, HAND2, PHOX2B, PHOX2A, and MYCN as the top five targets critical for the survival of cell lines." (PMID 37297004, 2023). "For example, ALX4 was found to bind the P3 site in human cranial neural crest cells; Phox2a enriched for P3 dimer sites in cortical motor neurons; and PHOX2B predominantly binds to only P3 sites in KELLY, BE2C, and CLBGA neuroblastoma cell lines." (PMID 41279221, 2025). "Significant expression of (nor-)adrenergic (“NOR”) markers (i.e., CHGA, CHGB, DBH, TH, PHOX2A, and PHOX2B) is common for healthy sympatho-adrenal cells and tumor NOR populations identified in low-risk neuroblastoma cases (FDR < 0.01, Welch’s t-test)." (PMID 34493726, 2021).
lung carcinoma (10 papers, 2016 to 2021). "In HPV16, A7730C, variant of sub-lineage A4, showed potentially effect to PHOX2A which is a transcription factor involving in cell proliferation and migration in lung cancer." (PMID 32677948, 2020). "The presence of A7730C variants in LCR, which was further shown to be a potential binding site for PHOX2A, a transcription factor involving in cell proliferation and migration in lung cancer, showed a high mutation frequency in cervical cancer." (PMID 28767682, 2017). "For example, miR-326 influences the aggressive ability of lung cancer cell through regulating paired-like homeobox 2a (phox2a)." (PMID 32425696, 2020). "MiR-326 reverses chemoresistance in human lung adeno-carcinoma cells by targeting specificity protein 1, and regulates cell proliferation and migration in lung cancer by targeting phox2a and is regulated by HOTAIR." (PMID 27816050, 2016). "PHOX2A was a transcription factor involving in cell proliferation and migration in lung cancer." (PMID 33941222, 2021). "Proto-oncogenes NOB1 and phox2a were also targeted by miR-326 in gastric cancer and lung cancer." (PMID 32766125, 2020). "MiR-326 could regulate cell proliferation and migration of lung cancer by targeting phox2a, CCND1 and NSBP." (PMID 27835574, 2016).
cervical carcinoma (2 papers, 2010 to 2017). A carcinoma arising from either the exocervical squamous epithelium or the endocervical glandular epithelium. "A7730C variant which showed a high mutation frequency in cervical cancer was predicted to be a binding site for the cellular transcription factor PHOX2A." (PMID 28767682, 2017). "In addition, A7730C variant, which showed a high mutation frequency in cervical cancer, was predicted to be a binding site for the cellular transcription factor PHOX2A." (PMID 28767682, 2017). "ALK, PHOX2B and PHOX2A resulted to be highly expressed in almost all analyzed NB cell lines with respect to a pool of normal tissues and to HeLa cells, a cervix carcinoma cell line characterized by low level of ALK expression and almost undetectable expression levels of the two PHOX2 genes." (PMID 20957039, 2010).
Anxiety (1 paper, 2025). Intense feelings of nervousness, tension, or panic often arise in response to interpersonal stresses. "The locomotor abilities in the OFT and the anxiety‐like behaviors remained unaffected by overexpression of Phox2a in the LSNTac1 neurons." (PMID 41204431, 2025).
congenital fibrosis of the extraocular muscles (1 paper, 2023). "Congenital fibrosis of the extraocular muscles (CFEOM) affects cranial nerves 3 and 4 and is caused by autosomal dominant missense variants in KIF21A, TUBB3, TUBB2B or TUBA1A or autosomal recessive variants in PHOX2A." (PMID 38500555, 2023).
endometrial cancer (1 paper, 2013). Primary or metastatic malignant neoplasm involving the endometrium (mucous membrane that lines the endometrial cavity). "All these results indicate that HAND2 and the interaction neighbourhood of HAND2, including GATA4, HEYL, and PHOX2A, represent a core component that is epigenetically deregulated in endometrial cancer." (PMID 24265601, 2013). "All EpiMods demonstrated strong enrichment for biological terms, with the HAND2 EpiMod itself highly enriched for other transcription factors (e.g., GATA4, HEY2, HOXD13, PHOX2A, HAND1), all of which were also hypermethylated in endometrial cancer." (PMID 24265601, 2013).
itch (1 paper, 2025). "This study investigates the role of paired‐like homeobox 2a (Phox2a) in tachykinin 1‐positive (Tac1+) neurons of the lateral spinal nucleus (LSN) as a novel target for histamine‐independent pruritus intervention." (PMID 41204431, 2025). "Given the downregulation of Phox2a in CQ‐induced itch, we next investigated the effects of Phox2a overexpression in the LSN neurons." (PMID 41204431, 2025). "However, in the CQ‐induced itch model, Phox2a overexpression selectively decreased sEPSC amplitude without altering its frequency." (PMID 41204431, 2025). "Phox2a expression in LSNTac1 neurons is selectively reduced in chloroquine‐induced itch." (PMID 41204431, 2025). "Conversely, decreased Phox2a expression in the context of CQ‐induced itch may enhance postsynaptic neuronal excitability and thereby contribute to the exacerbated itch behaviors." (PMID 41204431, 2025). "Overexpression of Phox2a alleviates this itch by the amplitude of spontaneous excitatory postsynaptic currents, revealing a potential treatment target for histamine‐independent pruritus." (PMID 41204431, 2025). "Next, we examined the effects of Phox2a overexpression on sEPSCs in itch models." (PMID 41204431, 2025). "Importantly, during CQ itch, Phox2a‐overexpressing LSNTac1 neurons exhibited a selective reduction in sEPSC amplitude, but not frequency, compared to mCherry‐expressing controls." (PMID 41204431, 2025). "Notably, Phox2a, expressed in LSNTac1 neurons, was downregulated during CQ‐induced itch." (PMID 41204431, 2025). "Notably, Phox2a expressed in the LSNTac1 neurons was distinctly reduced in CQ‐ but not His‐induced itch." (PMID 41204431, 2025).
lung diseases (1 paper, 2013). "The methyaltion frequencies of 7 genes: MYF6, SIX6, SOX1, RARB, BCL2, PHOX2A and FOLX2 were significantly higher in stage I NSCLC than in non-cancerous lung diseases." (PMID 23599765, 2013). "This study showed that 7 genes (MYF6, SIX6, SOX1, RARB, BCL2, PHOX2A and FOLX2) were frequently methylated in 101 cases of patients with stage I NSCLC, while rarely methylated in 30 patients with non-cancerous lung diseases." (PMID 23599765, 2013). "In this study, among the 7 genes which demonstrated hypermethylation in stage I NSCLC compared with non-cancerous lung diseases, 5 genes (MYF6, SIX6, PHOX2A, FOLX2 and SOX1) were found for the first time to be abonormally methylated in NSCLC." (PMID 23599765, 2013). "The methylation frequencies (29.70–64.36%) of 7 genes (MYF6, SIX6, SOX1, RARB, BCL2, PHOX2A and FOLX2) in stage I NSCLC were significantly higher compared with those in non-cancerous lung disease controls (P<0.05)." (PMID 23599765, 2013).
major depression (1 paper, 2025). "Both Phox2a and Phox2b proteins are highly expressed in LC in the brains of patients with major depression." (PMID 39876531, 2025). "Corticosteroid receptor blockers inhibit the expression of Phox2a/b and then regulate the norepinephrine phenotype to alleviate major depression." (PMID 39876531, 2025).
myeloma (1 paper, 2025). "We selected genes (PHOX2A, CDH2, and HTATIP2) whose methylation levels significantly changed to validate their expression via qRT‒PCR in CD138+ myeloma cells." (PMID 41146049, 2025).
tumour (7 papers, 2010 to 2025). "We undertook this by analysing the expression of NA markers that we characterised in Xenopus AVNA development (Ascl1, Hand2, Phox2a and TH) in NB primary tumours, using publicly available microarray data." (PMID 25786414, 2015). "MiR-326 is considered to be a tumor suppressor in several human cancers, since it could directly target downstream oncogenes, such as cyclin D1, phox2a, and Notch1." (PMID 35012553, 2022). "As no mutations have been observed in the PHOX2A regulatory or coding regions of tumour samples, it is likely that this gene is involved in the pathogenesis of NB when its expression is deregulated in either direction." (PMID 26902400, 2016). "We found that NB primary tumours have high expression of PHOX2A, HAND2 and TH." (PMID 25786414, 2015). "Recently, the PHOX2A gene has been localised to near the deletion breakpoint of a number of 11q-deleted NB specimens, and microarray expression analysis has shown that it is one of nine noradrenaline biosynthesis pathway genes whose expression is reduced in unfavourable NB tumours." (PMID 26902400, 2016). "Like PHOX2A, PHOX2B, is overexpressed in a number of tumours and NB cell lines." (PMID 26902400, 2016). "However, the possible contribution of PHOX2A to the pathogenesis of NB is not univocal as it is over-expressed in a number of NB tumours and cell lines." (PMID 26902400, 2016).
cancer (6 papers, 2013 to 2025). A tumor composed of atypical neoplastic, often pleomorphic cells that invade other tissues. "Twenty genes were found mutated orwith copy number alterations in at least five percent of three cancer cohortsand six of them (PHOX2A, NFYC, EST2, EIF2S1, SSRP1 and PARP1) associated withimpacted patient survival." (PMID 32159609, 2020). "Guided by the HTAN-SCLC cancer epithelium dataset, we further found that the RNA expression of ASCL1, PHOX2A and AR was regulated by ZNF536." (PMID 38720348, 2024). "The methylation of 4 genes, MYF6, SIX6, PHOX2A, FOLX2, has never previously been reported in any types of cancer." (PMID 23599765, 2013).
PHOX2A also shares sentences with these, for which no sentence is quoted: fibrosis of the (2 papers); Strabismus (2); Coronary artery disease (1); deafness (1); diabetes mellitus (1); Duane retraction syndrome (1); epilepsy (1); Ewing sarcoma (1); gastric cancer (1); horizontal gaze palsy with progressive scoliosis (1); lung adeno-carcinoma (1); multiple myeloma (1); neurodevelopmental disorder (1); non-small cell lung carcinoma (1); ptosis (1); schizophrenia (1); spinocerebellar ataxia (1); thyroid cancer (1).